CTLA4 (cytotoxic T-lymphocyte associated protein 4)
Diseases named in the same sentence as CTLA4 in open-access papers (continued):
Sharing a sentence is not in itself a finding about the gene and the disease.
cancer (continued). "This study also represents the largest prognostic model discovery project for cancer patients who received ICI treatment (either as monotherapy or as a combination of anti-PD-1 and anti-CTLA-4)." (PMID 35197093, 2022). "Co-receptors such as PD-1 and CTLA-4 inhibit the TCR-peptide-MHC signal, making them instrumental targets for antibody-blockade cancer immunotherapies." (PMID 35327505, 2022). "For example, ipilimumab, an anti-CTLA-4 antibody approved by FDA for treating cancers, induced a surprisingly high incidence of AH (4.5–10%) in cancer patients." (PMID 36499283, 2022). "In the present study, SRSF9 expression had been shown to positively correlate with most of the 47 immune checkpoint genes in most cancers, such as CD276, CD86, CTLA-4, and CD40." (PMID 35069733, 2022). "The expression of immune checkpoint (ICP) genes, such as PDCD1 (PD1), CD274 (PDL1), CTLA4, LAG3, and HAVCR2 (TIM3) has been utilized in predicting the response of patients to immune checkpoints therapy in a variety of cancers including PAAD." (PMID 35601487, 2022). "Over the last decade, ICIs have made a huge splash in cancer treatment by targeting immune checkpoints like PD‐L1, CD40, and CTLA‐4." (PMID 36083778, 2022). "Clinical trials, in increasing number, consider ADT in combination with cancer vaccine and immune checkpoint inhibitors (ICI), particularly for checkpoints CTLA-4 and PD-1." (PMID 35015785, 2022). "AP3S1 expression was positively correlated with most immunosuppressive genes in pan-cancer, such as CD274 (PD-L1), PDCD1 (PD-1), CTLA4, LAG3 and TIGIT." (PMID 35874816, 2022). "Established cancer immunotherapy targets PD1, PDL1, CTLA4, and CD27 were top hub genes in most constructed multi-omics GRNs." (PMID 36611894, 2022). "The present analysis found elevated expression of CD47 not only positively correlated with PD1, PD-L1, CTLA4, but also with multiple other immune checkpoints such as IDO1, CD40, CD160, CD86, CD44 across various cancer types." (PMID 35697717, 2022). "Therefore, the disruption by CTLA-4 blockade may provide cancer patients with therapeutic benefits." (PMID 35585567, 2022). "CTLA-4 and CD39 are co-expressed in most TILs Tregs, suggesting that those cells have a higher suppressive function compared to peripheral Tregs in cancer patients." (PMID 36338731, 2022). "We also assessed the correlations between DAAM2 and the expression of immune checkpoints, including TIGIT, CTLA4, CD274, and PDCD1, across cancers." (PMID 35281277, 2022). "Monoclonal antibodies-targeting CTLA-4, PD-1 or PDL-1 have shown clinical potential for effectively controlling and treating human cancers." (PMID 35592250, 2022). "The initial discovery of PD-1 and CTLA-4 led to several promising therapeutic drugs (e.g., Ipilimumab, the first immunotherapy drug that targets CTLA4) for cancer treatment." (PMID 36358857, 2022). "Immune checkpoint inhibitors have revolutionized cancer therapy, as a monotherapy or in various combinations; the three approved types are anti-PD-1, anti-PDL1, and anti-CTLA4 monoclonal antibodies." (PMID 35158822, 2022). "At present, PD-1/PD-L1, CTLA4, GAL3, IDO and other checkpoints have been paid more and more attention in cancer immunotherapy." (PMID 36405706, 2022). "Checkpoint blockade therapies (e.g., anti–PD-1, anti–CTLA-4, and anti–LAG-3 therapy, among others) have been developed for multiple cancers." (PMID 36612082, 2022). "We also demonstrated that TMEM59L expression was negatively linked with the expression of many immune modulators, including PD-L1, IDO1, TIGIT, CTLA-4, and BTLA in various cancers." (PMID 36618425, 2022). "Immune-related myositis (irMyositis), mostly affecting elderly male cancer patients soon after the initiation of ICI treatment, appears to be the most common neuromuscular toxicity of anti-PD-1/anti-PDL1 and anti-CTLA-4 immunotherapy." (PMID 36551575, 2022).
cancer (continued). "ICI, which blocks the binding of checkpoint proteins with their partner proteins and allows T cells to kill cancer cells, has been revolutionarily developed, since Yervoy, the first ICI and CTLA-4 inhibitor, was approved by the U.S. FDA in 2011." (PMID 35273607, 2022). "Current immunotherapy, including anti-CTLA-4, anti-PD-1/PD-L1, and chimeric antigen receptor (CAR) T-cell therapy, has significantly improved the survival outcomes of patients with cancers." (PMID 36090967, 2022). "Antibodies targeting PD-1 and CTLA-4 were approved by the FDA and were proven to be effective against several cancer types." (PMID 36189222, 2022). "In conclusion, we conducted a retrospective study on patients with malignancies who received ICI therapies such as anti-PD-1, PD-L1, and CTLA-4 antibodies." (PMID 36447159, 2022). "In this study, we found that patients in the low-risk subgroup had higher expression of common immune checkpoint molecules such as PD-1, PD-L1, LAG3, CTLA-4, PD-L2, and CD74, which are commonly expressed in human cancer." (PMID 35996170, 2022). "Specifically, we retrospectively analyzed the correlations among host, cancer and treatment characteristics with ICI response in advanced, solid tumor patients treated with PD-1, PD-L1, and/or CTLA-4 inhibitors." (PMID 35960456, 2022). "TME substances can induce angiogenesis and the development of cancer and metastasis, whereas the immune cells found in TME, namely, CTLA-4, PD1, PD-L1, LAG3, and VISTA participate in the antitumor immune response." (PMID 35744019, 2022). "Specifically, it is worth noting that SAAL1 was positively correlated with PD-L1, CTLA-4, and LAG-3 in most cancer types." (PMID 35963646, 2022). "We found that PTBP expression showed a strong correlation with PD-1, CTLA4, LAG3, or TIM-3 in pan-cancer." (PMID 36203873, 2022). "Identification of two cancer patients with monogenic CVID in this study, one with CTLA-4 insufficiency and another with NF-κB1 defect, comes in line with previous reports, suggesting the higher risk of malignancy in those monogenic disorders." (PMID 35250968, 2022). "Afterward, we evaluated the link between DTYMK expression and key immune checkpoints (CD274, CTLA-4, HAVCR2, LAG3, PDCD1, PDCD1LG2, SIGLEC15, and TIGIT) expression levels in pan-cancer." (PMID 36094557, 2022). "ICI cancer immunotherapy has revolutionized cancer treatment, with FDA approval of eight monoclonal antibodies to date blocking the PD-1, PD-L1, or CTLA-4 ICs with many more under investigation." (PMID 36876140, 2022). "PD-1, CTLA-4 and TIM-3 are upregulated on T cells during HIV, HBV, HCV, herpesviruses and cancer, resulting in altered metabolism, epigenetics, and responsiveness to cytokines." (PMID 36439147, 2022). "In the clinical treatment of tumors, immune checkpoints (for instance, CTLA-4, TIM-3, LAG-3, and most importantly, PD-1/PD-L1) have been demonstrated to be effective targets in cancer immunotherapy due to the ability thereof to regulate immune responses." (PMID 35585975, 2022). "Immune checkpoint modulators, such as anti-CTLA4 and anti-PD antibodies, and cultured immune cells such as CAR-T, have shown unexpected antitumor effects across a broad spectrum of cancer types in recent years." (PMID 36276870, 2022). "Here, we evaluated the correlation between three classic ICGs, CD274, CTLA4 and PDCD1, and MCM2 expression in 40 TCGA cancers." (PMID 35693940, 2022). "CTLA-4, PD1 (PDCD1), and PD-L1 (CD274) are targets of immunotherapy, and immune checkpoint blocking of these sites has revolutionized the paradigm of cancer therapy." (PMID 35771229, 2022). "Previous studies have shown that, among these genes, CTLA4, IGF2BP2, and TNFRSF4 are involved in cancer procession and affect the prognosis of patients with OSCC." (PMID 36185403, 2022). "Mice subcutaneously inoculated with LL2 cancer cells were treated with COS or an ICI cocktail consisting of anti-PD-L1 and anti-CTLA-4 antibodies." (PMID 35631632, 2022).
cancer (continued). "In response to complement-approved anti-PD-1/L1 and anti-CTLA-4 antibody therapies, the suppression of CD73 can enhance the therapeutic activity of monoclonal antibodies and repress immunotolerance of cancer cells." (PMID 35620732, 2022). "RALA was significantly correlated with the infiltration of B cells and macrophages, as well as the expression of immune checkpoint molecules such as CD274, CTLA4, HAVCR2 and LAG3, suggesting that RALA can be used as a kind of new pan-cancer immune marker." (PMID 36466919, 2022). "AP3S1 expression was positively correlated with most immunosuppressive genes in pan-cancer, such as the common CD274 (PD-L1), PDCD1 (PD-1), CTLA4, LAG3, and TIGIT." (PMID 35874816, 2022). "In this case, the effectiveness of anti-CTLA-4 varied with the expression status of CTLA-4 on effector CD8+ T cells and appeared less effective in human cancer trials." (PMID 36323740, 2022). "Using the immune system to fight cancer has become an effective treatment option, and immunotherapy represented by immune checkpoint blockade (ICB, PD-1/L1, and CTLA-4) has shown impressive clinical efficacy in several cancer types." (PMID 35042477, 2022). "Inhibitors of CTLA4 and TIM-3 can be applied as immunotherapeutic targets in the treatment of cancer patients." (PMID 35794622, 2022). "As CTLA-4 is a marker of T cell activation, its elevated expression indicates increased CD4+ T cell activation in the TME of these cancers." (PMID 36497170, 2022). "Among various cancers, the ccRCC had high level of CYT, which were increased in response to CTLA-4 and PD-L1 immunotherapy as well as CD8+ T cell activation." (PMID 35096270, 2022). "Cancer prognosis is importantly determined by immunosurveillance efficacy, which is critically influenced by the expression of immune checkpoint-related genes, such as PD-L1, CTLA-4, and LAG-3, in cancer cells." (PMID 35963646, 2022). "Our results suggested that in most types of cancer, SERCA3 expression was distinctly related to immune checkpoints, such as TLR4, ICOS, CTLA-4, PDCD1, and CD27." (PMID 36385955, 2022). "As it happens with other immune related pathways (e.g., TGF-B, CTLA-4, etc.) the role of NMD in cancer is complex, and sometimes with apparently controversial outcomes." (PMID 36443756, 2022). "CTLA-4, an inhibitory surface receptor expressed on activated Tregs, is the first FDA-approved ICIs for cancer treatment." (PMID 35804953, 2022). "The pan-cancer analysis revealed that PTPN7 was related to PD-L1 and CTLA-4 expression in almost all cancer types." (PMID 36226189, 2022). "Regulation of immune system by immune checkpoint blockade (ICB), such as anti-CTLA4, anti-PD1 and anti-PDL1, leads to durable responses in human pan-cancer." (PMID 35508972, 2022). "Current efforts to improve the efficacy of cancer immunotherapy are mainly focused on reversing T cell exhaustion by exploiting pathways such as the PD-L1/PD-1 signaling pathway and the CD80/-86/CTLA4 pathway." (PMID 35972800, 2022). "PDCD1, CD274, CTLA4, LAG3, C10orf54, and BTLA expression had positive correlations in most cancer types, and in approximately half of the cancer types, GBP1 expression is positively correlated with CD276 expression." (PMID 35222540, 2022). "For example, immunosuppressive checkpoint proteins such as PD-1, CTLA-4, LAG-3, TIM-3, and NKG2A/B and are often upregulated in cancer." (PMID 35205776, 2022). "CTLA4 and PDCD1 genes are two representative immune checkpoint genes, proven to have an excellent immune blocking effect in various cancers." (PMID 35281840, 2022). "Monoclonal antibodies can target immune checkpoints (e.g., PD-L1 and CTLA-4), tyrosine kinase and subsequent signaling pathways (e.g., VEGF), and cytokines in cancer patients (e.g. IL-6 and IL-1β)." (PMID 35054524, 2022).
cancer (continued). "The patient was enrolled in a trial that excluded patients with known HER2-positivity: AK104, a PD-1/CTLA-4 bispecific antibody, combined with chemotherapy (mXELOX) as first-line therapy for advanced gastric G/GEJ cancer (NCT03852251)." (PMID 36569905, 2022). "ICIs attempt to dampen the PD-1/PD-L1/1 and CTLA-4/CD80-CD86 interaction, restore immunosurveillance and aid the host’s immune system in fighting cancer." (PMID 35207516, 2022). "Through blockade of the T-cell inhibiting PD-L1 and CTLA-4, ICI as nivolumab, pembrolizumab, and ipilimumab are enhancing the immune responses against cancer." (PMID 35609553, 2022). "For cancer immunotherapy, T-cell immunoglobulin and TIGIT, as well as CTLA-4, PD-1, T-cell immunoglobulin 3 and lymphocyte activation gene 3, are the most commonly targeted checkpoints." (PMID 35659630, 2022). "Inonotus obliquus blocks CTLA-4/CD80 interaction and increases T cell activity so that cancer cells cannot escape the immune response." (PMID 36142412, 2022). "Therefore, the blockade of CTLA-4 may lessen therapeutic benefits in cancer patients." (PMID 36335094, 2022). "Antitumor immunity is also reduced by immune checkpoint molecules like CTLA-4, TIM3, PD-L1 and PD-1, and their combinational blockade has shown great promises for cancer treatment." (PMID 36153626, 2022). "MDSC accumulation in cancers also suppresses CD8+ T cell activation and hinders the efficacy of PD-1 and CTLA-4 checkpoint inhibitors." (PMID 35655772, 2022). "Cancer immunotherapies based on the targeting of immune checkpoints (PD-1, PDL1, and CTLA4) have shown clinical value in various cancer types." (PMID 35053610, 2022). "Through blockade of the T-cell inhibiting PD-L1 and CTLA-4, ICI are enhancing the immune responses against cancer." (PMID 35609553, 2022). "The FDA approval of anti-PD-1 mAbs pembrolizumab and nivolumab, and anti-CTLA-4 mAb ipilimumab has improved the lives of many CRC patients and indicates the significant anti-cancer potential of IT." (PMID 35205776, 2022). "Antibody drugs against immune checkpoint proteins, including PD-L1, PD-1 and CTLA4, are FDA approved for treating a wide range of cancers." (PMID 36575439, 2022). "The emergence of immunotherapy has shed light on cancer therapy; TMB and immune checkpoints, such as PD-L1, CTLA-4, LAG3, TIM3, and TIGIT, act as gatekeepers or biomarkers of immune responses." (PMID 35493104, 2022). "Immune checkpoint molecules, including PD-1/PD-L1, CTLA-4, and LAG-3, play significant roles in mediating T-cell dysfunction during cancer progression and suppressing antitumor immunity." (PMID 36230887, 2022). "Immune checkpoints, including the cytotoxic T-lymphocyte antigen 4 (CTLA-4), provide inhibitory signals, which inactivate cytotoxic CD8+ T cells that are a key player in the anti-cancer immune response." (PMID 33078260, 2021). "Checkpoint blockade immunotherapy (CBI), such as anti-CTLA-4 and anti-PD-1/PD-L1, works to reactivate the CD8 T cells and can lead to better patient outcomes in multiple cancer types." (PMID 33653826, 2021). "We found that CD161 was positively correlated with marker genes of exhausted T cells, immune activating genes, and immunosuppressive genes in pan-cancer such as TIGIT, PDCD1, LAG3, CTLA4, STING1, CD96, and IDO1." (PMID 34305920, 2021). "This review compiles the current strategies of vascular modulation to improve the efficacy of different immunotherapies: PD-1/PD-L1 and CTLA-4 antibodies, CAR T cells and cancer vaccines." (PMID 34680355, 2021). "The combination of sch rhIL-15 with both anti-CTLA4 and anti-PD-L1 was tested in the CT26 and MC38 colon carcinoma and in the Transgenic Adenocarcinoma Mouse Prostate C2 (TRAMP-C2) cancer models in mice." (PMID 33671252, 2021). "Treg depletion by anti-CTLA-4 mAbs decreases the immunosuppression in the TME, but it also results in severe cancer immunotherapy-related adverse events." (PMID 34806028, 2021).
cancer (continued). "The mAbs by targeting checkpoints CTLA-4 and PD-1/PD-L1 have achieved the US Food and Drug Administration (FDA) approval for the treatment of different cancers." (PMID 34917131, 2021). "Immune checkpoint blocking therapy for CTLA4 and PD1 has become an effective method for treating various malignant tumours." (PMID 33557848, 2021). "Here we found that the expression of CTLA-4 and TIM-3 in hypoxic patients increased, indicating that the hypoxic TME would promote the immune escape of cancer cells." (PMID 34895169, 2021). "CTLA-4, PD1, and its ligand (PDL1) are the principal human inhibitory immune checkpoints that have been overexpressed in a broad range of cancers and are the main target molecules for CPI cancer therapy." (PMID 35083014, 2021). "TIGIT expression also positively correlated with CTLA4, PDCD1 (PD-1), CD274 (PD-L1), ICOS in most of the cancer types." (PMID 34795387, 2021). "Immunotherapies with checkpoint blockade antibodies targeting PD-1, PD-L1, and cytotoxic T-lymphocyte antigen 4 (CTLA-4) have remarkably improved the outcome of patients with advanced NSCLC and other cancers." (PMID 34095230, 2021). "Methylation of CpGs annotated to the promoters of LAG3, CTLA4, CD86, CD80, and HAVCR2 also decreases with age pan-cancer." (PMID 34433020, 2021). "A combination of PDT and ICI using antibodies against PD1/PDL1, CTLA4 and IDO have been investigated in preclinical studies using murine cancer models of breast, colon, renal, lung and skin, to show significant improvements in therapeutic efficacies." (PMID 34068491, 2021). "CTLA-4 inhibition is also able to broaden and remodel the peripheral TCR repertoire, as it was observed in cancer patients undergoing ipilimumab treatment." (PMID 33406696, 2021). "The results showed that the five TLR4 prognosis-related cancers KIRC, SKCM, STAD, TGCT, and UCEC were related to ICOS, CTLA4, CD28, and CD80." (PMID 34631699, 2021). "The expression of immune checkpoint genes [e.g., PDCD1 (PD1), CD274 (PDL1), CTLA4, LAG3, and HAVCR2 (TIM3)] has been utilized in predicting the response of patients to ICB therapy in a variety of cancers including CC." (PMID 34733790, 2021). "Although CTLA4 and PD1-PDL1-targeted cancer immunotherapy has had a profound impact on the treatment of CC, treatment is ineffective in a large proportion of patients." (PMID 33557848, 2021). "In light of the revolutionizing outcomes obtained with the blockade of PD-1 or CTLA-4 pathways, the limited efficacy of KIR-blockade in cancer patients is underwhelming." (PMID 34503073, 2021). "Despite the promising impact of cancer immunotherapy targeting CTLA4 and PD1/PDL1, numerous cancer patients fail to respond." (PMID 34267742, 2021). "The results revealed that CD161 was positively correlated with marker genes of exhausted T cells, immune activating genes, and immunosuppressive genes in pan-cancer, such as TIGIT, PDCD1, LAG3, CTLA4, STING1, CD96, and IDO1." (PMID 34305920, 2021). "Recent immunotherapies have used PD-1, CTLA4, and TIGIT inhibitors to enhance T cell response in cancer patients." (PMID 35069521, 2021). "CTLA-4 upregulation and binding with CD80/CD86 promotes T cell anergy, and cancer cells and TAMs have been shown to express CD80 and CD86." (PMID 34803925, 2021). "T cells in the TME of advanced cancer showed increased expression of PD1, CTLA4, CD39, PD-L2, LAG3, TIGIT, Tim3 and decreased expression of CD73." (PMID 34135436, 2021). "Therefore, clinically meaningful cancers have several mechanisms involved in immunosuppression, such as enhancing different cells to participate in immunosuppression and enhancing various molecules to participate in immunosuppression, including CTLA4, PD1, PDL1, LAG3 and other immune checkpoints." (PMID 33557848, 2021). "Further studies are needed to characterize the tissue signals that modulate CTLA-4 expression by ILC and how anti-CTLA-4 antibodies impact their function in cancer." (PMID 34885076, 2021).